PLK1 (polo like kinase 1)
Diseases named in the same sentence as PLK1 in open-access papers (continued):
Sharing a sentence is not in itself a finding about the gene and the disease.
metastatic cancer (4 papers, 2017 to 2023). A carcinoma which has spread from the original site of growth to another anatomic site. "Moreover, the expression of PLK1 can be useful in the diagnosis of patients with a high risk of metastasis, because the levels of PLK1 are higher in patients with metastatic cancer than in patients with primary cancer." (PMID 36793862, 2023). "The group reported that the expression of all potential substrates including HDAC1, Plk1 and Aurora A were higher in metastatic cancer cells than in normal cells." (PMID 29179506, 2017). "Therefore, PLK1 is a useful index of malignancy and advanced metastatic cancer for diagnostics, prognostics, and therapeutics in clinics." (PMID 36793862, 2023). "Next, we wanted to determine whether the suppression of TNFAIP6 could block cell migration and invasiveness in active PLK1-driven metastatic cancer." (PMID 31548612, 2020). "In addition, we found that of the 9 samples from metastatic cancer, 3 had high PLK1 (higher than the median)." (PMID 31741706, 2019).
papillary thyroid carcinoma (4 papers, 2004 to 2024). "We conducted an analysis of PLK1 protein expression in a large cohort of samples from papillary thyroid carcinoma (PTC) patients and examined its functional significance in PTC cell lines, both in vitro and in vivo." (PMID 38361222, 2024). "One explanation of these results is that PLK1 plays an oncogenic role and is constitutively required in papillary carcinoma during the early phase, while it is less necessary for the development of this carcinoma during the advanced stage." (PMID 14735186, 2004). "This means that the physiological significance of PLK1 in thyroid papillary carcinoma is unique and completely different from that in all other carcinomas studied to date." (PMID 14735186, 2004). "Papillary carcinoma overexpressed PLK1 more frequently than follicular carcinoma (P=0.0002), and 38 cases were judged in the high group (43.7%)." (PMID 14735186, 2004). "A high incidence of PLK1 overexpression was observed in papillary carcinoma." (PMID 14735186, 2004). "Lanes 1–5 indicated papillary carcinoma, and lanes 2, 3, and 5 were positive for PLK1." (PMID 14735186, 2004). "In summary, the findings of this study strongly suggest that PLK1 plays a constitutive role in thyroid papillary carcinoma especially during the early phase, and may be related to the malignant transformation of this lesion." (PMID 14735186, 2004). "However, in this carcinoma, PLK1 overexpression was seen only in two of the 17 cases (11.8%), and the incidence was significantly lower than that in papillary carcinoma (P=0.0143)." (PMID 14735186, 2004). "Furthermore, we compared PLK1 expression and Ki-67 LI in papillary carcinoma." (PMID 14735186, 2004). "Although the mechanism of malignant transformation from normal follicle to papillary carcinoma remains to be elucidated, our finding that PLK1 is frequently overexpressed in incidental carcinomas suggests that PLK1 expression may even play a role in the carcinogenesis of papillary carcinoma." (PMID 14735186, 2004). "The findings of several studies show that PLK1 is unlikely to contribute directly to the mitosis of papillary carcinoma cells." (PMID 38260150, 2023). "According to these findings, we can conclude that PLK1 is not likely to contribute directly to the mitosis of papillary carcinoma cells." (PMID 14735186, 2004). "Coexpression of PLK1 and Ki-67 was only occasionally seen, and we could not establish any relationship between PLK1 expression and Ki-67 LI in papillary carcinoma." (PMID 14735186, 2004).
pulmonary arterial hypertension (4 papers, 2019 to 2024). Pulmonary arterial hypertension (PAH) is a group of diseases characterized by mean pulmonary artery pressure >20 mmHg and elevated pulmonary arterial resistance leading to right heart failure. "To investigate the role of PLK1 in PH, we checked the expression of PLK1 in mice with pulmonary hypertension." (PMID 37598171, 2023). "In addition, little is known of FOXM1 and PLK1 interactions and their participation in driving vascular cell growth in pulmonary hypertension." (PMID 31437238, 2019). "BRD4 expression is elevated in patients with idiopathic pulmonary arterial hypertension (PAH) and promotes the upregulation of polo-like kinase 1 (PLK1) via forkhead box M1 (FoxM1)." (PMID 39215370, 2024).
uterine corpus endometrial carcinoma (4 papers, 2017 to 2023). A endometrial carcinoma (disease) that involves the body of uterus. "First, based on bioinformatics analysis, PLK1 mRNA levels in uterine corpus endometrial carcinoma samples from TCGA database were examined, and PLK1 overproduction was observed in cancer samples." (PMID 36626982, 2023).
Alzheimer disease (3 papers, 2011 to 2017). A progressive, neurodegenerative disease characterized by loss of function and death of nerve cells in several areas of the brain leading to loss of cognitive function such as memory and language. "PLK1 is also expressed in neural progenitor cells and gradually diminishes during neurogenesis, but is increased in brain cells of Alzheimer disease patients." (PMID 26880286, 2016). "Moreover, misexpression of PLK-1 has been shown to be responsible for triggering fatal diseases, such as Alzheimer's disease and tumorigenesis." (PMID 28415805, 2017). "Therefore, in the present review, we have discuss the role of PLK-1 and the substrates involved in the regulation and control of DNA replication, transcription, translation, ciliogenesis, Alzheimer's disease (AD), checkpoint adaptation, recovery, and apoptosis during DDR." (PMID 28415805, 2017).
B-cell acute lymphoblastic leukemia (3 papers, 2020 to 2025). A neoplasm of lymphoblasts committed to the B-cell lineage, typically composed of small to medium-sized blast cells. "An example is the siRNN targeting Polo-like kinase 1 (Plk1), which is highly overexpressed in pediatric patients with B-cell acute lymphoblastic leukemia (B-ALL)." (PMID 40943628, 2025).
brain cancer (3 papers, 2017 to 2022). A primary or metastatic malignant neoplasm affecting the brain. "It has been reported that the level of PLK1 in GBM is elevated, and its inhibition limits the growth of brain cancer cells." (PMID 31763067, 2019).
chronic myelomonocytic leukemia (3 papers, 2021 to 2025). A myelodysplastic/myeloproliferative neoplasm which is characterized by persistent monocytosis, absence of a Philadelphia chromosome and BCR/ABL fusion gene, fewer than 20 percent blasts in the bone marrow and blood, myelodysplasia, and absence of PDGFRA or PDGFRB rearrangement. "RAS mutations drive proliferative chronic myelomonocytic leukemia through the lysine methyltransferase 2A (KMT2A)–Polo-like kinase 1 (PLK1) axis." (PMID 40906088, 2025). "Beyond AML, PLK1 inhibition might have a role in chronic myelomonocytic leukemia (CMML) with higher expression of PLK1 in patients with RAS-pathway mutations." (PMID 34194628, 2021).
ciliopathies (3 papers, 2012 to 2024). "Of note, Plk1 was also associated to another ciliopathy, the nephronophthisis (NPH), a cystic kidney disease." (PMID 26579493, 2015). "Further studies focused on the identification of ciliary substrates of Plk1 would help to understand the specific function of the ciliary Plk1 and its role in the pathogenesis of ciliopathies." (PMID 22701722, 2012). "Importantly, our study suggests a role for Plk1 in the pathogenesis of nephronophthisis and related ciliopathies." (PMID 22701722, 2012).
cutaneous melanoma (3 papers, 2017 to 2025). A primary melanoma arising from atypical melanocytes in the skin. "The cell cycle regulator PLK1 is associated with cancer progression and correlates with patient survival in cutaneous melanoma, although the mechanisms remain unclear." (PMID 41284701, 2025). "Polo-like kinase 1 (PLK1), a critical cell cycle regulator, is associated with cancer progression and negatively correlates with patient survival in cutaneous melanoma based on clinical database analysis." (PMID 41284701, 2025). "In The Cancer Genome Atlas (TCGA), we found a significant correlation (r = 0.5; p ≤ 0.0001) between EZH2 and PLK1 expression in the cutaneous melanoma cohort." (PMID 36768289, 2023).
diabetes (3 papers, 2024 to 2025). "Concurrently, ON-01910inhibits Polo-like kinase 1 (Plk1), engaging in the shared molecular mechanisms of cell proliferation and inflammation, thus paving a new route for the treatment of diabetes and atherosclerosis." (PMID 38715799, 2024). "Additional studies are also required to determine whether increased PLK1 activation plays a role in the development of sexual dysfunction in conditions such as hypertension and diabetes." (PMID 41227386, 2025).
HIV-1 infection (3 papers, 2008 to 2022). The type species of lentivirus and the etiologic agent of acquired immunodeficiency syndrome (AIDS). "Moreover, G2,M arrest caused by HIV-1 infection strongly correlated with a disruption in 14-3-3 θ binding to centrosomal proteins, Plk1 and centrin." (PMID 18445273, 2008). "While wild-type HIV-1 infection resulted in a massive decrease in 14-3-3 θ-associated centrosomal proteins, infection with vif-vpr- mutant HIV-1completely restored Plk1 and centrin association with 14-3-3 θ to levels observed in uninfected cells." (PMID 18445273, 2008). "Although nuclear levels did not change, Vprv, but not HIV-1 infection, significantly increased cytoplasmic expression specifically of CyclinB1 and Polo-like kinase 1 (Plk1), but not Cdc25C and Cdk1." (PMID 18445273, 2008). "Interestingly, the binding of 14-3-3 θ to centrosomal proteins, centrin and Plk1, is disrupted in HIV-1 infection but not in adriamycin treated cells." (PMID 18445273, 2008).
liver fibrosis (3 papers, 2020 to 2023). "In our study, we found that increased PLK1 expression was associated with liver fibrosis and generated reliable data to support the pro‐fibrosis effect of PLK1." (PMID 32463161, 2020). "They further reported that blocking PLK1 effectively suppressed liver fibrosis by inhibiting hepatic stellate cell activation." (PMID 37269004, 2023). "The current study demonstrates that inhibition of PLK1 expression prevents HSCs activation and proliferation to reduce liver fibrosis through the Wnt/β‐catenin signalling pathway." (PMID 32463161, 2020). "Collectively, these observations revealed that inhibition of PLK1 alleviates liver fibrosis and the activation of HSCs in vivo." (PMID 32463161, 2020). "In CCl4‐induced liver fibrosis mice, we found that reduced expression of PLK1 by AAV‐shPLK1 significantly decreased liver fibrosis." (PMID 32463161, 2020). "We demonstrated that PLK1 was increased in human liver fibrosis samples and primary HSCs from CCl4‐induced fibrosis mice using Western blot and real‐time PCR, whereas immunofluorescence and IHC assays further showed PLK1 was up‐regulated in the cytoplasm." (PMID 32463161, 2020). "In the present study, we found that PLK1 expression was elevated in primary HSCs isolated from CCl4‐induced liver fibrosis mice and LX‐2 cells stimulated with TGF‐β1." (PMID 32463161, 2020). "To define the role of PLK1 in liver fibrogenesis, we investigated the functional effects of PLK1 on liver fibrosis in CCl4‐induced liver fibrosis mice in vivo." (PMID 32463161, 2020). "Considering this combined effect, PLK1 promoted the activation and proliferation of HSCs and inhibited apoptosis in liver fibrosis." (PMID 32463161, 2020). "Immunohistochemical analyses revealed low expression of PLK1 in healthy livers, whereas much higher expression of PLK1 was evident in the perivascular region of the portal vein and lesion boundary in patients with liver fibrosis." (PMID 32463161, 2020). "We found that inhibition of PLK1 expression could reduce the activation of HSCs and thus alleviate liver fibrosis." (PMID 32463161, 2020). "Our present study suggests that PLK1 is an attractive novel therapeutic target for liver fibrosis." (PMID 32463161, 2020). "Together, blocking PLK1 effectively suppressed liver fibrosis by inhibiting HSC activation, which may provide a new treatment strategy for liver fibrosis." (PMID 32463161, 2020). "To further assess whether PLK1 expression is related to HSCs activation in liver fibrosis, we investigated the functional effects of silencing PLK1 on liver fibrosis in LX‐2 cells in vitro." (PMID 32463161, 2020). "We conclude that PLK1 is an important molecule for HSCs activation in liver fibrosis." (PMID 32463161, 2020). "In our study, we investigated whether PLK1 regulates HSCs via the Wnt/β‐catenin signalling pathway to influence the development of liver fibrosis." (PMID 32463161, 2020). "We analysed PLK1 levels in human healthy control and liver fibrosis tissue." (PMID 32463161, 2020). "To evaluate whether PLK1 expression is correlated with liver fibrosis, we developed a CCl4‐induced mouse liver fibrosis model for histopathological studies." (PMID 32463161, 2020). "Interestingly, inhibition of TGF‐β1 signalling decreased PLK1 expression, suggesting that a PLK1‐mediated Wnt/β‐catenin signalling axis plays an important role in the process of liver fibrosis by enhancing the activation of HSCs by TGF‐β1." (PMID 32463161, 2020). "Taken together, our analyses suggest that inhibiting PLK1 promotes the apoptosis of HSCs by mitochondrial‐ and caspase‐dependent pathways in vivo and in vitro, providing evidence that inhibiting PLK1 ameliorates liver fibrosis." (PMID 32463161, 2020). "Interestingly, the results revealed a dramatic up‐regulation of PLK1 (red) expression in the activated HSCs that were positive for α‐SMA (green) after the induction of liver fibrosis by CCl4." (PMID 32463161, 2020).
liver fibrosis (continued). "Moreover, BRD4 could promote PLK1 expression through P300/H3K27ce, thereby enhancing hepatic stellate cells activation and hepatic fibrosis." (PMID 37980502, 2023). "Our results suggest that PLK1 may be a potential therapeutic target for liver fibrosis." (PMID 32463161, 2020). "Knockdown of PLK1 inhibited α‐SMA and Col1α1 expression and reduced the activation of HSCs in CCl4‐induced liver fibrosis mice and LX‐2 cells stimulated with TGF‐β1." (PMID 32463161, 2020). "We found that low expression of PLK1 by AAV‐shPLK1 significantly decreased the expression of β‐catenin, c‐Myc and Cyclin D1 in CCl4‐induced liver fibrosis mice compared with AAV‐empty mice." (PMID 32463161, 2020). "Protein expression of PLK1, α‐SMA and Col1α1 was elevated in human liver fibrosis compared with healthy livers by Western blotting." (PMID 32463161, 2020). "Furthermore, we found an increase in PLK1, α‐SMA and Col1α1 mRNA and protein levels in primary HSCs isolated from CCl4‐induced liver fibrosis mice compared with vehicle mice." (PMID 32463161, 2020). "Moreover, low expression of PLK1 by AAV‐shPLK1 led to a significant decrease in the expression of α‐SMA and Col1α1 protein in HSCs from CCl4‐induced liver fibrosis mice." (PMID 32463161, 2020). "Similarly, the mRNA levels of PLK1 and fibrogenic genes (α‐SMA, Col1α1 and TIMP‐1) were higher in liver fibrosis than in healthy livers, as shown by real‐time PCR." (PMID 32463161, 2020). "In addition, we revealed that inhibition of PLK1 promoted HSC apoptosis and reduced liver fibrosis via the Wnt/β‐catenin signalling pathway in vivo and in vitro." (PMID 32463161, 2020).
microcephaly (3 papers, 2012 to 2022). A congenital or acquired developmental disorder in which the circumference of the head is smaller than normal for the person's age and sex. "Together, Treacle and Plk1 are critically required for proper cortical neurogenesis, which has important implications in the regulation of mammalian brain size and the pathogenesis of congenital neurodevelopmental disorders such as microcephaly." (PMID 22479190, 2012).
myeloid leukemia (3 papers, 2013 to 2020). A clonal proliferation of myeloid cells and their precursors in the bone marrow, peripheral blood, and spleen. "Recently, PLK1 has started to be considered a possible therapeutic target also in myeloid leukemias, since it is overexpressed in the majority of AML cells and these cells respond to PLK1 inhibitors in vitro and in vivo." (PMID 23520509, 2013). "In this study, we identified PLK1 as a possible oncoprotein target in pediatric AML patient samples and human myeloid leukemia cell lines." (PMID 25574601, 2015). "A novel multi-peptide-based vaccination targeting PLK1 and survivin simultaneously along with PD1 blockade led to complete tumour eradication and long-term survival in mice with clonally heterologous C1498 myeloid leukaemia." (PMID 32595211, 2020).
myeloid neoplasm (3 papers, 2021 to 2022). Proliferation of myeloid cells originating from a primitive stem cell. "PLK1 (volasertib and onvansertib) inhibitors have completed clinical trials for patients with myeloid neoplasms (MDS and AML) with reasonable safety data, prompting us to establish the therapeutic efficacy of these agents in pCMML models." (PMID 34006870, 2021).
pulmonary fibrosis (3 papers, 2023 to 2024). Chronic progressive interstitial lung disorder characterized by the replacement of the lung tissue by connective tissue, leading to progressive dyspnea, respiratory failure, or right heart failure. "In vivo studies have shown that inhibition of PLK1 alleviates pulmonary fibrosis induced by BLM in mice by inhibiting the proliferation of pulmonary fibroblasts." (PMID 38343538, 2024). "Among the top compounds predicted to be therapeutic for IPF by the in silico approach, we selected BI2536, a polo-like kinase (PLK) 1/2 inhibitor, as a candidate for treating pulmonary fibrosis using an in silico analysis." (PMID 37269004, 2023). "In the present study, we demonstrated that PLK1 expression was upregulated in fibroblasts, PLK1 inhibition suppressed fibroblast proliferation, and PLK1 inhibition ameliorated experimental pulmonary fibrosis in mice." (PMID 37269004, 2023). "In this study, we selected the PLK1/2 inhibitor BI2536 as a candidate for the treatment of pulmonary fibrosis using an in silico analysis." (PMID 37269004, 2023). "FOXM1 plays a major role in regulating the development of lung fibrosis by inducing the expression of the proliferation-related genes CCNB1, CCND1, and PLK1." (PMID 37238726, 2023). "To investigate why selective PLK1 inhibition ameliorated lung fibrosis in bleomycin-treated mice, we next examined whether or not GSK461364 treatment affected the number of inflammatory cells and lymphocyte fractions in BALF." (PMID 37269004, 2023). "However, the effect of PLK1 inhibition on pulmonary fibrosis has never been investigated." (PMID 37269004, 2023).
pulmonary hypertension (3 papers, 2019 to 2023). Increased pressure within the pulmonary circulation due to lung or heart disorder. "In sum, our present results illustrate that the increased expression of FOXM1 and PLK1 in PAH leads directly to increased expression of CDC2 resulting in potentiated growth hyperactivity of PASMC from patients with pulmonary hypertension." (PMID 34203295, 2021).
rectal tumor (3 papers, 2015 to 2021). "Polo-like kinase 1 scores (immunohistochemistry) in rectal tumour centre and periphery." (PMID 26047016, 2015). "We propose that the tumour periphery be used as the sampling site for rectal tumour PLK1 scoring." (PMID 26047016, 2015). "In the in vivo experiments, BTF3-siRNA inhibited the growth of rectal tumors, and in the microarray, we confirmed that BTF3 regulated the cell cycle related gene (MAD2L2, MCM3, and PLK1)." (PMID 31263147, 2019).
skin cancer (3 papers, 2012). "Using the Oncomine database, the analysis of the transcriptome of human cell lines and xenografts with sensitivity to drugs designed against AURKA, AURKB or PLK1 kinases show a profile similar to that seen in the described mouse skin carcinomas." (PMID 22880004, 2012).